AHR (aryl hydrocarbon receptor)
Diseases named in the same sentence as AHR in open-access papers (continued):
Sharing a sentence is not in itself a finding about the gene and the disease.
renal fibrosis (30 papers, 2017 to 2026). A final common manifestation of a wide variety of chronic kidney diseases characterized by glomerulosclerosis and tubulointerstitial fibrosis. "On the other hand, ARNT, a transcriptional co-activator of AhR, has been implicated in renal fibrosis and is sought as a therapeutic target in CKD; strong experimental support exists for a mechanistic model in which FK506 induces renoprotection." (PMID 33415104, 2020). "A possible connection between AhR and renal fibrosis has been further supported by the association between indole solutes and renal fibrosis, which may be mediated by AhR signaling." (PMID 33415104, 2020). "IAld treatment ameliorated renal injury by inhibiting AHR pathway in rats with renal fibrosis and 1-hydroxypyrene-stimulated HK-2 cells." (PMID 41522358, 2026). "This rebalancing strengthens intestinal barrier integrity, inhibits oxidative stress, and downregulates aryl hydrocarbon receptor (AhR)-mediated inflammation and renal fibrosis." (PMID 41000396, 2025). "IS and PCS, as protein-bound uremic toxins, exacerbate tubular injury and renal fibrosis through activation of the aryl hydrocarbon receptor (AhR) pathway, significantly impacting advanced CKD stages due to reduced renal clearance." (PMID 41503356, 2025). "Dietary 5',7',3',4',5'‐pentahydroxy flavanone and barleriside A alleviated the decline in renal function and renal fibrosis in 5/6 nephrectomized rats by inhibiting AhR activation." (PMID 38491448, 2024). "Subsequently, we first demonstrated that IAld administration ameliorated renal fibrosis by suppressing AHR signaling." (PMID 39098923, 2024). "Taken together, L. johnsonii supplementation protected against renal fibrosis through inhibiting AHR signaling pathway via increasing IAld level." (PMID 39098923, 2024). "Fourthly, we found IAld-produced specific L. johnsonii and reveal L. johnsonii-produced IAld that affect renal fibrosis via inhibiting AHR pathway in CRF and UUO rats as well as 1-hydroxypyrene (HP)-stimulated HK-2 cells." (PMID 39098923, 2024). "Disturbances in tryptophan metabolism are frequently reported in CKD patients, leading to worsening renal fibrosis and the progression of CKD, by causing metabolites to activate the aryl hydrocarbon receptor." (PMID 39877349, 2024). "Collectively, these results demonstrated that microbial-derived IAld improved renal function and abolished renal fibrosis through attenuating AHR signaling." (PMID 39098923, 2024). "Our earlier publication showed that poricoic acids abolished AHR, IƙB/NF-ƙB and Keap1/Nrf2 pathways in mice with renal fibrosis." (PMID 39239643, 2024). "Studies have shown that AHR activation is involved in the pathogenesis of several renal diseases, including renal fibrosis and glomerular injury." (PMID 37510393, 2023). "An increase in AhR activity—in the periglomerular region and in proximal and distal renal tubules—under the action of adenine and indoxyl sulfate leads to renal fibrosis." (PMID 35743162, 2022). "Recently, many reports have suggested the intestinal metabolites of tryptophan activate the aryl hydrocarbon receptor (AHR) signaling pathway, which can induce oxidative stress and inflammation and mediate renal fibrosis." (PMID 35308536, 2022). "EDCs cause proteinuria, affect eGFR, perturb the intracellular REDOX balance, and activate apoptosis and AHR pathways, eventually resulting in kidney injury and renal fibrosis." (PMID 36668758, 2022). "It indicated that 1-AP and 1-HP were demonstrated to mediate renal fibrosis through activation of the aryl hydrocarbon receptor signaling pathway and the endogenous 1-AP and 1-HP are novel mediators of CKD progression." (PMID 34992536, 2021). "Exposure to adenine and IS increases AhR activity in the periglomerular region as well as in proximal and distal renal tubules, leading to renal fibrosis." (PMID 33415104, 2020).
renal fibrosis (continued). "Substantial evidence has shown that renal fibrosis is linked to hyperactive pro-fibrotic molecular players, such as the renin-angiotensin system (RAS), reactive oxygen species (ROS), Toll-like receptor 4 (TLR4), and aryl hydrocarbon receptor (AHR) 22-25." (PMID 41522358, 2026). "Moreover, gut-microbiota-derived tryptophan metabolism mediates renal fibrosis through aryl hydrocarbon receptor signaling activation." (PMID 40277929, 2025). "Consequently, IS accumulates and induces endothelial oxidative stress and renal fibrosis through activation of the aryl hydrocarbon receptor (AhR)/nuclear factor kappa-B (NF-κB) pathway." (PMID 40735439, 2025). "Our previous publications have demonstrated that some compounds such as matairesinol, rhoifolin, 5,6,7,8,3′,4′-hexamethoxyflavone, 5,7,3′,4′,5′-pentahydroxy flavanone and erythro-guaiacylglycerol-β-ferulic acid ether attenuated renal fibrosis by suppressing AHR signalling." (PMID 39239643, 2024). "In kidneys of mice with unilateral ureteral obstruction-induced renal fibrosis, an increase in AhR mRNA level was accompanied by significant increases in the expressions of AhR target genes, including Cyp1a1, Cyp1a2 and Cyp1b1, suggesting AhR signaling pathway activation in mouse kidneys." (PMID 38491448, 2024). "Tubular‐specific knockout of AhR mitigated cell senescence and renal fibrosis." (PMID 38940381, 2024). "Collectively, naturally derived compounds, such as AHR inhibitors, attenuated renal fibrosis." (PMID 39239643, 2024). "However, to date, only a few studies have shed light on the impact of tryptophan metabolites on fibrosis modulation through AhR, especially for renal fibrosis and cardiac fibrosis." (PMID 35656117, 2022). "The AhR signaling pathway has been reported to exacerbate aging phenotypes in different tissues, and here, we mainly focus on how tryptophan metabolism accelerates renal fibrosis via AhR." (PMID 35656117, 2022). "Poricoic acid ZM, ZP inhibits the expression of NF-κB and its downstream genes, promotes the expression of the Nrf2 signaling pathway, regulates AHR signaling pathway, attenuates oxidative stress and inflammatory response in the kidney, and treats renal fibrosis." (PMID 35978370, 2022). "Numerous studies have revealed and considered natural AhR agonists and antagonists as alternative therapies for improving CKD and inhibiting renal fibrosis." (PMID 38491448, 2024). "Because the prolonged activation of HIF signaling in renal epithelial cells leads to renal fibrosis, it is possible that IDO has a renoprotective effect also by activating AhR." (PMID 28877670, 2017). "Therefore, AhR−/− mice produce fewer DHA crystals that precipitate in the tubule interstitial compartment, and consequently have less inflammation and renal fibrosis." (PMID 32260098, 2020). "Furthermore, AhR has been reported to promote fibrillar collagen degradation by activating MMP1/MMP3 in fibroblasts, but whether it has a similar effect on renal fibrosis, idiopathic pulmonary fibrosis, hepatic fibrosis and cardiac fibrosis remains to be determined." (PMID 35656117, 2022).
endothelial dysfunction (29 papers, 2016 to 2025). In vascular diseases, endothelial dysfunction is a systemic pathological state of the endothelium (the inner lining of blood vessels) and can be broadly defined as an imbalance between vasodilating and vasoconstricting substances produced by (or acting on) the endothelium. "In our previous studies, EPFR induced endothelial dysfunction and impaired lung function in a manner intricately associated with pulmonary oxidative stress and activation of the aryl hydrocarbon receptor (AhR)." (PMID 40214911, 2025). "IS and PCS activate the aryl hydrocarbon receptor (AhR) signaling in vascular cells, causing endothelial dysfunction and arterial stiffness." (PMID 41503356, 2025). "Since the overexpression of the AhR/NF-κB signaling pathway is associated with oxidative stress and endothelial dysfunction, further studies investigating the treatment target of AhR are warranted in patients with LTBI." (PMID 40508196, 2025). "Along the same lines, we show that AhR activation leads to a reduction of eNOS activity and migratory capacity in human primary endothelial cells (EC), features associated with endothelial dysfunction." (PMID 26790370, 2016). "Elevated AHR activity also contributes to vascular injury, heightening the risk of thrombotic complications, stroke, and myocardial injury via mechanisms involving oxidative stress and endothelial dysfunction." (PMID 40949107, 2025). "With endothelial dysfunction increasingly recognized as a hallmark of chronic inflammatory disease, our data point towards a potential role for AHR activation through dietary ligand supplementation as a therapeutic strategy to facilitate organ homeostasis and disease resilience." (PMID 37586410, 2023). "Our prior research employing AT-II cell-specific AhR knockout mice demonstrated that EPFR inhalation promotes endothelial dysfunction in arteries peripheral to the lungs by activating AhR at the air-blood interface." (PMID 40214911, 2025). "This study aimed to investigate exosomal miRNA as systemic mediators linking AhR activation at the air-blood interface with EPFR-induced endothelial dysfunction in arteries peripheral to the lung." (PMID 40214911, 2025). "In mice selectively deficient in AhR expression in alveolar type-II (AT-II) cells, specialized epithelial cells residing at the air-blood interface in the lung, EPFR-induced endothelial dysfunction observed downstream of the lung was abolished." (PMID 40214911, 2025). "Our previous studies identified that AhR activation in alveolar epithelial cells at the air-blood interface regulates endothelial dysfunction observed distal to the lungs, potentially through the release of systemic mediators." (PMID 40214911, 2025). "We also observed that activation of the aryl hydrocarbon receptor (AhR) in the alveolar type-II (AT-II) cells that form the air-blood interface stimulates the release of systemic factors that promote endothelial dysfunction in vessels peripheral to the lung." (PMID 40214911, 2025). "IS activates the aryl hydrocarbon receptor (AhR) mediating oxidative stress and endothelial dysfunction via activation of the CYP1A1 pathway." (PMID 35202128, 2022). "An example of this is benzo[a]pyrene (B[a]P), which is considered to have a low affinity for AhR, but with potent effects on Ca2+ induction, a mechanism related to endothelial dysfunction." (PMID 36136462, 2022). "Numerous studies have also reported that IS had detrimental effects on endothelial cells and was described as an endotheliotoxin to induce multiple processes such as pro-inflammatory, pro-oxidative, AhR activation and endothelial dysfunction." (PMID 34941711, 2021). "The pathogenesis induced by AhR varies among cardiovascular diseases, but includes inflammatory responses, immune responses, oxidative stress, and endothelial dysfunction." (PMID 29984241, 2018).
endothelial dysfunction (continued). "In summary, our findings support that miRNA may be systemic mediators promoting endothelial dysfunction mediated via EPFR-induced AhR activation at the air-blood interface." (PMID 40214911, 2025). "Several reports indicate that the blockade of the IS-aryl hydrocarbon receptor (AhR) signaling pathway may protect endothelial cells from ischemic insult and reduce endothelial dysfunction." (PMID 38534325, 2024). "Also, indole derivatives, produced from microbial metabolism of tryptophan, exert anti-inflammatory effects by activating the aryl hydrocarbon receptor (AhR), thereby reducing endothelial dysfunction and vascular inflammation." (PMID 39596530, 2024). "It has also been suggested that the agonistic properties of the aryl hydrocarbon receptor (AhR), endothelial dysfunction, and IS-induced prothrombotic effects may also indirectly lead to neuronal damage." (PMID 37108238, 2023). "Therefore, in our endothelial cell model, the effects of kynurenine are mediated by AhR, which is also the known target of another tryptophan-derived uremic toxin, indoxyl sulfate, in promoting calcification and endothelial dysfunction in both valvular interstitial aortic cells and the endothelium." (PMID 40864097, 2025). "Further experiments using the AhR antagonist CH223191 suggested that activation of AhR by clozapine might contribute to endothelial dysfunction as it diminished the impairment of vasodilation to ACh at any concentration and largely improved the maximal vasodilator response." (PMID 34979820, 2022). "We therefore assessed whether AhR plays a role in ZnONPs-mediated endothelial dysfunctions." (PMID 32414036, 2020). "Furthermore, overexpression of AhR has been shown to induce endothelial dysfunction." (PMID 31439044, 2019). "Thus, it has been speculated that increased AhR expression could result in vascular inflammation through induction of iNOS and thereby further contribute to endothelial dysfunction and vessel aging." (PMID 31439044, 2019). "Thus, higher AhR expression could result in vascular inflammation through this pathway and thereby further contribute to endothelial dysfunction and vessel aging." (PMID 26790370, 2016). "Thus, high level AhR expression in the large vessels could contribute to endothelial dysfunction, which is in line with our findings presented here." (PMID 26790370, 2016). "Additional studies are critical for understanding the link between AhR activation in AT-II cells in pulmonary miRNA biogenesis and systemic release and the specific roles of these miRNAs in EPFR-induced endothelial dysfunction observed peripheral to the lung." (PMID 40214911, 2025). "Dysregulated enzyme activity in the NAD de novo pathway increases the levels of circulating tryptophan metabolites that activate AHR, resulting in poly-ADP ribose polymerase activation, thrombosis, endothelial dysfunction, and immunosuppression." (PMID 37814337, 2023). "AhR activation seems to be responsible, at least in part, for endothelial dysfunction in patients with CKD since uremic toxins such as IS and IAA, as AhR agonists lead to increased oxidative stress and vascular inflammation." (PMID 37686342, 2023). "who report that high glucose level rapidly activates AhR in endothelial cells, and that AhR further controls the expression of the TSP-1 protein, triggering endothelial dysfunction and vascular disease." (PMID 36418969, 2022). "Using pathway analysis, we found that 5 of these AhR-dependent miRNA appear to play roles in modulating the endothelin-1 and endothelial nitric oxide signaling pathways, two pathways important in EPFR-induced endothelial dysfunction." (PMID 40214911, 2025). "Moreover, with higher doses of cystine we observed an increase in AhR expression and activation (CYP1A1) and there is strong evidence on the role of AhR activation by exogenous and endogenous metabolites in endothelial dysfunction in vitro and in vivo." (PMID 34573115, 2021).
endothelial dysfunction (continued). "It has been postulated that under hyperglycemic conditions, AhR complexes with specific transcriptional factors, early growth response (EGR-1), and activator protein-2 (AP-2), that mediate changes in ECs gene expression, leading to endothelial dysfunction and other vascular diseases." (PMID 36418969, 2022).
liver fibrosis (29 papers, 2014 to 2026). "For instance, specific knockout of AhR in HSCs is sufficient to trigger spontaneous liver fibrosis in mice and enhance their susceptibility to chemically induced fibrosis." (PMID 41585883, 2025). "The AhR activator dioxin was found to enhance collagen deposition and aSMA, preluding to liver fibrosis, and was implicated in the basal expression of matrix metalloproteinase 1 by fibroblasts, which is crucial in collagen remodelling." (PMID 38506079, 2024). "We show that a single injection of a normally nonlethal dose of TCDD to TiparpH532A induces a lethal wasting syndrome characterized by increased AHR signaling, steatohepatitis, liver fibrosis, and loss of WAT." (PMID 34129049, 2021). "Downregulation of AhR during the progression of liver fibrosis is associated with decreased expression levels of phase I and II enzymes and drug transporters during inflammation-related signal transduction between AhR and other nuclear receptors." (PMID 30477109, 2018). "AhR is highly expressed in the liver, while the role of AhR in hepatic fibrosis is controversial since both loss and gain of AhR expression could lead to hepatic fibrosis." (PMID 35656117, 2022). "Indole-3-acetate may ameliorate hepatic fibrosis by inhibiting the release of pro-inflammatory cytokines through an AhR-associated mechanism." (PMID 35656117, 2022). "However, the role of AHR in liver fibrosis remains controversial, as both loss and exacerbation of AHR activity seem to induce liver fibrosis." (PMID 34075438, 2021). "Analysis of hepatic transcriptional profiles of MCD and GNMTKO mice reveals novel association of the transcriptional regulators STAT5b, AhR, and ARNT with liver fibrosis." (PMID 41519232, 2026). "Activities of RXRa and AHR were also decreased; RXRa represses liver fibrosis by blocking hepatic stellate cell activation and proliferation, while AHR modulates inflammasome activation through inhibition of NF‐kB." (PMID 39605182, 2025). "In studies of human and mouse hematopoietic stem cells, we found that AhR can block the activation of hematopoietic stem cells and the expression of genes required for liver fibrosis." (PMID 41019044, 2025). "Consistent with previous studies, we found that AHR significantly alleviates CCL4‐induced liver fibrosis by inducing ferroptosis in mHSCs." (PMID 39654034, 2024). "In a mouse model of liver fibrosis, AhR activation was shown to trigger the expression of several MMPs and collagens." (PMID 39180052, 2024). "AHR activated by 2,3,7,8‐tetrachlorodibenzo‐p‐dioxin (TCDD) can cause hepatotoxicity and activate HSCs, leading to liver fibrosis." (PMID 39654034, 2024). "Our previous study also reported that OTA also induced hepatic fibrosis and aryl hydrocarbon receptor (AhR)-regulated hepatotoxicity in liver tissues of mice." (PMID 37505742, 2023). "In CDAA-HF-T(−)-T versus control, the upregulated signaling pathways included those related to hepatic fibrosis, inflammatory cytokines (mainly interleukin (IL)-8), chemokines, and exogenous chemical metabolism involving the aryl hydrocarbon receptor." (PMID 37535625, 2023). "Chronic alcohol consumption is an important contributor to liver-related deaths, while alcohol-induced hepatic fibrosis was reversed by AhR agonists generated by tryptophan metabolism in the intestine." (PMID 35656117, 2022). "On the other hand, AhR activation sensitized mice to hepatic fibrosis by regulating profibrotic pathways." (PMID 35656117, 2022). "Whereas in immune-mediated liver disease, the current literature rather suggests an immunosuppressive function of AHR, the role of AHR in liver fibrosis or NASH remains ambiguous." (PMID 34075438, 2021). "Blocking of IL-22 production by administration of an AHR antagonist inhibited fibrogenesis in mouse models of liver fibrosis." (PMID 34075438, 2021).